EPO (erythropoietin)
Diseases named in the same sentence as EPO in open-access papers (continued):
Sharing a sentence is not in itself a finding about the gene and the disease.
kidney damage (32 papers, 2011 to 2025). "Cisplatin also causes kidney damage, decreases renal erythropoietin, and inhibits erythropoiesis (renal anemia)." (PMID 38152275, 2023). "EPO was found to increase the rate of kidney damage and the T allele of rs1617640 has been described as a ‘risk factor’ for DKD (odds ratio, 1.5)." (PMID 33976959, 2021). "We postulated that the protective benefits of EPO against TAA-induced kidney damage could be linked to its ability to regulate the JAK/STAT system." (PMID 37697015, 2023). "It was proposed that severe nephropathy might lead to a reduction in the production of erythropoietin, resulting in a loss of its neurotrophic effects." (PMID 36932648, 2023). "The reduced RBC, hemoglobin, and HCT are the result of nephropathy and reduced erythropoietin (EPO), as kidneys are responsible for the synthesis of EPO, a hormone involved in hematopoiesis." (PMID 40291032, 2025). "We constructed an injury‐responsive EPO‐producing (iREP) element that senses signals of kidney damage and drives the synthesis and secretion of native EPO." (PMID 41179707, 2025). "Instead, our findings suggest that kidney damage resulting from SLC7A7 dysfunction decreases erythropoietin production, leading to impaired erythropoiesis and iron accumulation." (PMID 39881295, 2025). "First, it plays a critical role in red blood cell (RBC) production as a significant component of hemoglobin to cater for erythropoietin insufficiency due to kidney damage, signifying its importance." (PMID 40880952, 2025). "PM2.5 can induce nephrotoxicity and kidney damage, and then lower the secretion of erythropoietin (EPO)." (PMID 35060058, 2022). "So, we detected and compared the indicators of biochemical, renal histopathological features, inflammation, and apoptosis, after pretreatment with VD3 or EPO, I/R kidney damage did tend to alleviation." (PMID 33953855, 2021). "Canagliflozin in diabetic patients with nephropathy leads to an increase in reticulocyte count, erythrocyte count, and hematocrit, which is mediated by EPO." (PMID 34708130, 2021). "Due to the multifactorial nature of IR-induced kidney damage, this study was designed to investigate the effect of concomitant administration of EPO and NAC with an IPC regimen on renal IR injury." (PMID 31342735, 2019). "In renal anemia patients, anemic and pathological hypoxia is ineffective toward EPO induction due to the inappropriate over-activation of PHDs in REP cells transformed into myofibroblasts (MF-REP cells) due to kidney damage." (PMID 31798631, 2019). "Meanwhile, Siwu granules ameliorate adenine-induced kidney damage to help rhEPO increase exogenous EPO directly to promote erythropoiesis." (PMID 31915448, 2019). "Kaynar and colleagues, studied the role of erythropoietin (EPO) in prevention of amikacin-induced nephropathy, to explore whether erythropoietin was renoprotective in amikacin-induced nephropathy in a rat model." (PMID 25340119, 2013). "In this study, it was found that application of IPC alone or in combination with EPO and NAC significantly attenuated kidney damage." (PMID 31342735, 2019). "Studies have shown that EPO therapy can reduce urinary L-FABP levels in CKD patients, suggesting that effective EPO treatment may help mitigate some of the oxidative stress and kidney damage." (PMID 39518373, 2024). "It has been widely reported, including our previous studies that HBSP, a non-erythropoietic peptide derived from EPO, remarkably ameliorated IR-induced kidney damage with notable improvement in cell death." (PMID 37207230, 2023). "On the other hand, there was another report which reported that plasma erythropoietin level was increased, but the expected reticulocyte response was decreased in diabetic subjects without nephropathy." (PMID 21754928, 2011). "It has been reported that plasma erythropoietin level was increased, but the expected reticulocyte response was decreased in diabetic subjects without nephropathy." (PMID 21754928, 2011).
kidney damage (continued). "Diabetic patients without nephropathy have an appropriate erythropoietin response to hypoxia." (PMID 25695026, 2014).
Splenomegaly (32 papers, 2006 to 2026). Abnormal increased size of the spleen. "In this study, to elucidate the underlying mechanisms, we employed transcriptomic analysis, which revealed a strong association between EPO-induced splenomegaly and immunosuppression of the spleen." (PMID 40191193, 2025). "In contrast to EPO neutralization and red blood cell transfusion, adenine-induced kidney injury almost blocked G-CSF–associated splenomegaly and significantly increased the compressive strength of spleens in mice treated with G-CSF." (PMID 33234677, 2021). "Longer illness duration and splenomegaly are factors associated with a lower D0 Hb which in turn is a stimulus for increased erythropoietin production." (PMID 23777546, 2013). "Additional agents – including thalidomide, hepcidin agonists, and inducers – have been reported to improve ineffective erythropoiesis and, in combination with erythropoietin, to increase hemoglobin levels and reduce splenomegaly in murine models." (PMID 41563495, 2026). "Elevated EPO levels have been positively correlated with marrow hyperplasia and splenomegaly, underscoring its role in the compensatory but maladaptive response in β-thalassemia." (PMID 41517557, 2025). "High dose EPO treatment leads to splenomegaly, possibly due to EPO stimulating the proliferation and aggregation of certain immune cells in the spleen, altering its tissue structure and increasing its volume." (PMID 40191193, 2025). "EPO treatment resulted in splenomegaly, spleen microstructure disorder, splenic corpuscular atrophy, indistinct germinal center, and unclear boundary between white and red pulp structures." (PMID 40191193, 2025). "For that, a higher level of suspicion must be held for fertile-age women who present with normal Hb and Htc levels and significant iron depletion, in the presence of low serum erythropoietin or splenomegaly." (PMID 36779103, 2023). "Our recently published work using this model demonstrated that repeated injection of EPO rapidly induced erythrocytosis, splenomegaly, and moderate vascular occlusions in WT mice in 3 weeks." (PMID 36719747, 2023). "In this subset of patients, the presence of splenomegaly, low serum erythropoietin, or elevated RBC count is a key factor for raising suspicion of masked PV, despite normal Hb and Htc." (PMID 36779103, 2023). "In both cases, the infected mice develop typical splenomegaly and erythroblastosis, with proliferating proerythroblasts being rendered erythropoietin-independent (SFFVP) or hypersensitive to erythropoietin (SFFVA)." (PMID 36527061, 2022). "Similar to mice, EPO administration to rats resulted in marked splenomegaly (471 ± 81 mg for the control group and 1744 ± 211 mg for the EPO-treated group)." (PMID 35682577, 2022). "To unequivocally determine the role of splenic erythropoiesis in G-CSF–induced splenomegaly and fragility rupture of spleen, we monitored the effects of high-dose EPO injections on the spleens in G-CSF–treated mice with kidney injury." (PMID 33234677, 2021). "It has been shown that transgenic mice carrying a 3'UTR-truncated Hmga2 cDNA showed proliferative hematopoiesis, erythropoietin-independent erythroid colony formation, as well as hypercellular bone marrow and splenomegaly." (PMID 27861570, 2016). "The pathology of splenomegaly involves a complex interplay of host-pathogen interactions, with LPS and EPO playing important roles." (PMID 26068006, 2015). "Vhl gene inactivation rapidly resulted in a marked splenomegaly and skin erythema, accompanied by renal and hepatic induction of the erythropoietin (Epo) gene, indicative of the in vivo activation of the oxygen sensing HIF pathway." (PMID 21811636, 2011). "In both strains, JAK2 V617F, but not JAK2 WT, induced non-fatal polycythemia characterized by increased hematocrit and hemoglobin, reticulocytosis, splenomegaly, low plasma erythropoietin (Epo), and Epo-independent erythroid colonies." (PMID 17183644, 2006).
Splenomegaly (continued). "Our study findings indicate that long term high-dose EPO treatment may lead to splenomegaly and immunosuppression of the local immune microenvironment in mice." (PMID 40191193, 2025). "RNA-Seq was performed to explore the possible mechanism of splenomegaly induced by EPO." (PMID 40191193, 2025). "Long term high-dose EPO treatment may lead to splenomegaly and immunosuppression of the local immune microenvironment in mice." (PMID 40191193, 2025). "When using this model, we found that EPO treated mice showed significant splenomegaly." (PMID 40191193, 2025). "Furthermore, these animals exhibit both splenomegaly and increased splenic erythropoiesis, which suggests that loss of IRP1 in these animals leads to the increased renal production of EPO and EPO-dependent extramedullary erythropoiesis (i.e., erythropoiesis occurring outside the bone marrow)." (PMID 25835049, 2015). "In addition, Salmonella infection has been shown to initiate extramedullary erythropoiesis and splenomegaly with increases in RBC precursors and EPO production." (PMID 28507548, 2017). "In EPO group, all mice were found splenomegaly, while no splenomegaly was found in the Veh group." (PMID 40191193, 2025). "The adjusted ferritin(ASF), erythropoietin(EPO), cardiac function, liver transaminase, hepatitis antibody, and peripheral blood T cell polarization were detected and the results of myelofibrosis, splenomegaly, and cyclosporine were collected and comparative analyzed in patients." (PMID 35680627, 2022).
Cognitive impairment (31 papers, 2016 to 2025). Abnormal cognition is characterized by deficits in thinking, reasoning, or remembering. "A meta-analysis of EPO in NE suggested a reduction in risk of brain injury, CP, and cognitive impairment." (PMID 40661891, 2025). "In summary, the present study suggests a novel pathogenic link between SZ and cognitive impairments, where EPO deficiency upregulates GADD45b triggering p38 MAPK activation and apoptosis in SZ, thus leading to the synaptic damage and cognitive impairments." (PMID 39467064, 2024). "EPO supplementation mitigated apoptosis, synaptic damage, and cognitive impairments caused by MK801." (PMID 39467064, 2024). "A novel etiopathogenic mechanism of SZ‐related cognitive impairments is uncovered, driven by EPO deficiency and the activation of the GADD45b/p38 MAPK axis." (PMID 39467064, 2024). "This single systematic review explored prevention of cognitive impairment in preterm neonates and found prophylactic erythropoietin (rhEPO) reduced the risk of neurocognitive impairment at 18–26 months." (PMID 38302917, 2024). "These EPO doses result in an improvement in cognitive deficits and reduction in cerebral Aβ; however, they are associated with a significant increase in hematocrit after 4 to 12 weeks of dosing." (PMID 37111315, 2023). "More recently, a meta-analysis determined that EPO alleviates the cognitive deficits associated with bipolar disorder, major depression, and schizophrenia without producing a significant unfavorable impact." (PMID 34987412, 2021). "Taken together, these behavioral tests suggest that EPO deficiency may be linked to SZ‐related cognitive impairments." (PMID 39467064, 2024). "Together, these data suggest that EPO deficiency may be involved in SZ‐related cognitive impairments by activating the GADD45b‐related apoptosis pathway." (PMID 39467064, 2024). "Moreover, cognitive impairment prevention in preterm infants found that prophylactic use of erythropoietin (rhEPO) demonstrated a significant risk reduction, from 20 to 14%." (PMID 38302917, 2024). "Moreover, overexpression of GADD45b significantly diminished the protective effects of EPO in MK801‐induced SZ, strongly supporting that the increase in GADD45b is required for EPO deficiency‐related synaptic and cognitive deficit in SZ." (PMID 39467064, 2024). "In this report, we demonstrated that EPO deficiency led to SZ‐related cognitive impairments." (PMID 39467064, 2024). "Razak and Hussain have showed that the use of EPO in neonates with perinatal hypoxic-ischemic encephalopathy may reduce the risk of mortality, cerebral palsy, cognitive impairment, and brain injury in meta-analysis." (PMID 33178833, 2020). "Previous studies have reported that EPO, alone or combined with other treatments, may reduce tau phosphorylation associated to different cognitive disorders." (PMID 33043002, 2020). "Thus, our study not only uncovers a novel role of EPO and GADD45b in the pathological and behavioral abnormalities associated with SZ but also identifies their potential application as therapeutic targets in SZ‐related cognitive deficits." (PMID 39467064, 2024). "The beneficial effect of SGLT2i is also related to their effect on lipid metabolism, graft function, erythropoietin production, cognitive impairment, and gut microbiota." (PMID 40649730, 2025). "In this study, we used the MK801‐induced SZ rat model to show that EPO levels were significantly decreased, correlating with cognitive impairments." (PMID 39467064, 2024). "Supplementation of EPO demonstrated significant improvements in synaptic damage and cognitive impairments in SZ." (PMID 39467064, 2024). "However, the role of EPO deficiency in SZ‐associated cognitive deficits remains unclear." (PMID 39467064, 2024).
Cognitive impairment (continued). "While our recent mouse studies provide a firm basis for ALTIBRAIN, and our longstanding work on EPO treatment of cognitive impairment across animals and humans lends significant support, the translation of findings from animals to humans is often poor." (PMID 39363230, 2024). "For instance, GH administration attenuated cognitive deficits in juvenile rats exposed to chronic and intermittent hypoxia, and this was associated with activation of IGF-1, EPO, and VEGF-A mRNAs in the hippocampus." (PMID 36232848, 2022). "Extremely preterm children with sustained elevations in inflammation-related proteins and EPO during the first postnatal month were also more likely to have cognitive impairment at 10 years." (PMID 34077474, 2021). "Previously, the possible effect of EPO as a potent neuroprotective agent on motor and cognitive impairments induced by HE were also identified." (PMID 32341967, 2019). "Administration of erythropoietin, a potent neuroprotective agent, immediately after postnatal exposure to sevoflurane reduces both activation of neural apoptosis and cognitive impairment at a later age." (PMID 31354415, 2019). "Erythropoietin (EPO) is a candidate treatment for cognitive impairment in unipolar and bipolar disorders (UD and BD) and modulates cognition-related neural activity across a fronto-temporo-parietal network." (PMID 31824247, 2019). "The evidence to date suggests that EPO has potential clinical utility to reduce cognitive deficits in patients with depression." (PMID 30310078, 2018). "The important role of EPO in cognition and mood disorders sheds light on the longstanding treatment challenge in psychiatric patients who suffer from chronic cognitive deficits." (PMID 30310078, 2018). "Here we investigated the possible protective effect of erythropoietin (EPO) on cognitive impairments induced by bilateral renal ischemia (BRI)." (PMID 29881418, 2018). "Taken together, extended EPO treatment restores executive function and prevents microstructural brain abnormalities in adult rats with cognitive deficits in a translational preclinical model of infant TBI." (PMID 29971038, 2018). "We just summarize some possible mechanisms of EPO but further studies are needed to clarify the exact mechanisms of EPO neuroprotection in a BRI model of cognitive impairments." (PMID 29881418, 2018). "In conclusion, Extended EPO treatment restores executive function and prevents microstructural brain abnormalities in adult rats with cognitive deficits in a translational preclinical model of infant TBI." (PMID 29971038, 2018). "Following TBI, EPO treatment reduces cognitive deficits, brain edema, proinflammatory cytokines, infiltration and activation of immune/inflammatory cells, and increases anti‐inflammatory cytokines." (PMID 29201540, 2017). "The SZ rats exhibited cognitive impairments and synaptic damage, indicating that modulating EPO may be a therapeutic option for SZ‐related cognitive impairments." (PMID 39467064, 2024). "In addition, supplementation of EPO improved synaptic and cognitive impairments by reducing GADD45b in SZ." (PMID 39467064, 2024). "Moreover, cerebral EPO is a crucial hormone in regulating the brain to maintain neuronal networks, working properly when challenged by hypoxia, and preventing cognitive deficits." (PMID 37373327, 2023). "EPO leads to increased cholinergic function and as its result, improvement of cognitive deficits." (PMID 29881418, 2018). "Notwithstanding, this highlights the major limitation of this treatment, since a large proportion of patients have somatic co-morbidities and EPO may therefore only become relevant for treatment of cognitive impairments in a subgroup of patients (if the study finds positive effects)." (PMID 30400939, 2018). "Amelioration of cognitive impairment by up-regulating the CaMKIIα/CREB/BDNF pathway and EPO/EPOR pathways." (PMID 36875644, 2023).
Cognitive impairment (continued). "In ELGAN study subjects, endogenous EPO concentrations at 2 weeks of life, regardless of intermittent or sustained systemic inflammation, were associated with low mental and/or psychomotor development indices and microcephaly at 2 years and with cognitive impairment at 10 years." (PMID 34077474, 2021). "A sustained EPO+MLT regimen, similar to the one used here, prevents chronic motor, social, behavioral and cognitive deficits in adult rats following prenatal CAM." (PMID 30319361, 2018). "Although prior studies of endogenous EPO in preterm infants have considered associations with inflammatory proteins, diseases of prematurity and cognitive impairment, none has assessed brain injury as a function of endogenous EPO status over time using MRI prior to NICU discharge." (PMID 34077474, 2021). "First, we aim to investigate whether 12 weekly recombinant human EPO infusions ameliorate cognitive impairments in first-degree relatives without psychotic or mood disorders to patients with BD, recurrent UD, or schizophrenia (sub-study 1)." (PMID 30400939, 2018).